SRC (SRC proto-oncogene, non-receptor tyrosine kinase)
Diseases named in the same sentence as SRC in open-access papers (continued):
Sharing a sentence is not in itself a finding about the gene and the disease.
prostate carcinoma (80 papers, 2008 to 2025). A carcinoma that arises from epithelial cells of the prostate gland. "Activation of SRC signaling is associated with recurrence of prostate cancer." (PMID 35317831, 2022). "Some of the genes that have been linked to the development of prostate cancer are PIK3R1, SRC, STAT3, HSP90AA1, AKT1, MAPK1, SESR1, and AR." (PMID 39114070, 2024). "Using chloroquine as an autophagy inhibitor enhances sensitivity of prostate cancer cells to SRC inhibitors." (PMID 35317831, 2022). "Here, we report, for the first time, that TUBB3 is phosphorylated at Tyrosine 340 (Y340) by c-SRC in prostate cancer cells." (PMID 35631517, 2022). "More importantly, FBXL7 depletion strikingly increased the metastasis of pancreatic and prostate cancer cells in multiple orthotopically transplanted mouse models in a manner dependent of c-SRC." (PMID 35906197, 2022). "SRC promotes initiation of prostate cancer which is dependent on posttranslational palmitoylation and membrane localization." (PMID 36228719, 2022). "We examined PTK6 and SRC in three prostate cancer cell lines (LNCaP, C4-2B, and PC3) and in breast (T47D) and lung (PC-9) cancer cell lines." (PMID 36228719, 2022). "Consistent with our findings, c-MYC was activated, whereas c-SRC was inhibited via downregulated miR-206/613 in prostate cancer cell." (PMID 34857003, 2021). "Interference with lipidation showed efficacy in in vivo model where blocking myristoylation of SRC inhibited its kinase activity and suppressed prostate cancer progression." (PMID 33572160, 2021). "Prostate cancer metastasis formation is, among other proteins, influenced by EphA2, steroid receptor coactivator (SRC) family tyrosine kinases, FAK, PKM2, TGFβ, TNFα, and chemokine signaling at every step of the metastatic process." (PMID 33572160, 2021). "The link between YAP1 and SRC in prostate cancer specifically indicates that the prostate cancer stroma has not been explicitly implicated." (PMID 32066485, 2020). "This study demonstrates the role of YAP1, TEAD1 and SRC in the conversion of NFs to CAFs in prostate cancer." (PMID 32066485, 2020). "We found that EPH and SRC over-expressions are common in highly aggressive prostate cancer cells, high-grade tumors, and circulating tumor cells from patients with biochemical recurrence, consistent with previous studies." (PMID 31805710, 2019). "Our data demonstrated that EPHB4 inhibition decreased the level of SRC and also positively correlated with SRC kinase in prostate cancer patients." (PMID 31641103, 2019). "An inverse relationship has been observed between androgen receptor (AR) activity and SRC signaling in advanced prostate cancer (PCa); however, the modulation of AR/SRC crosstalk that leads to metastatic PCa is unclear." (PMID 27028864, 2016). "Together, these findings indicate that prostate cancer cells expressing GFRA1 respond to GDNF stimulation with the activation of the SRC/ERK pathway and increased mitotic rates." (PMID 25575823, 2015). "Performing a functional genomics screen, we found that downregulation of SRC inhibitory kinase CSK is sufficient to overcome growth arrest induced by depriving human prostate cancer cells of androgen." (PMID 26091350, 2015). "Tr-KIT is aberrantly expressed in a subgroup of prostate cancer (PCa) patients and its expression correlates with enhanced activation of SRC and elevated expression and high tyrosine phosphorylation of SAM68." (PMID 26273626, 2015). "Recent work has indicated that the SRC genes are subject to amplification and over-expression in different human cancers, in particular in steroid hormone-promoted breast and prostate cancers." (PMID 24705462, 2014). "Our results are consistent with others that show that SRC is a potential miR-203 target gene, where we showed an inverse correlation between miR-203 and SRC expression in a RAS mutation prostate cancer model." (PMID 25004126, 2014).
prostate carcinoma (continued). "SRC is highly expressed in prostate cancer cell lines, and in vitro studies have shown decreased proliferation, invasion, and migration after exposure to SRC inhibitors." (PMID 23863691, 2013). "Stigmasterol, isoboldine, and β-sitosterol could target key prostate cancer-related hub genes (e.g., SRC, FGFR1, HSP90AA1); stigmasterol showed the strongest binding to HSP90AA1, and pathway analysis highlighted involvement of PI3K/AKT signaling." (PMID 41158126, 2025). "Similarly, the CXCL1-LCN2 axis has been linked to the induction of epithelial-mesenchymal transition (EMT) and SRC signaling activation in prostate cancer cells." (PMID 38167009, 2024). "The inhibitory effect of 7-O-galloyltricetiflavan (P15) on six bacterial species may be mediated through the lipid and atherosclerosis pathway, prostate cancer, adherens junctions, and targets such as SRC, MAPK1, and AKT1." (PMID 36770996, 2023). "Therefore, SRC inhibitors have been developed for prostate cancer therapy, but drug resistance has restricted their potential." (PMID 35317831, 2022). "Our study reveals a novel regulatory mechanism of prostate cancer AR inhibitor resistance, raises the possibility of AR/SRC dual-targeting of castration-resistance of prostate cancer, and lays foundation for the future development of selective inhibitors of GDF15 glycosylation." (PMID 35853851, 2022). "Furthermore, GDNF stimulation increased the proliferation rate of prostate cancer cells and activated the signal pathway through GFRα1/SRC pathway, which was related to the expression level of GFRα1, but not related to RET." (PMID 35582425, 2022). "It seems that autophagy is involved in resistance of prostate cancer cells to SRC inhibitors." (PMID 35317831, 2022). "The roles of SRC in the nuclear compartment of the prostate cancer cells remains to be explored." (PMID 33503805, 2021). "The changes in cell proliferation and the activation of the SRC/ERK pathway in prostate cancer cells upon stimulation with GDNF indicated that GDNF could also have an effect on the survival of prostate cancer in the context of cancer-directed therapeutics." (PMID 25575823, 2015). "Conversely, depletion of SRC curtails the growth of prostate cancer xenografts in castrated mice." (PMID 26091350, 2015). "In vivo studies have also demonstrated reduced prostate cancer growth with SRC inhibitors." (PMID 23863691, 2013). "A large body of evidence has implicated SRC, a non-receptor tyrosine kinase, as an important target in prostate cancer." (PMID 23863691, 2013). "High protein expression of YAP1 and SRC are commonly observed in high Gleason grade prostate cancer clinical specimens, and positively correlates with a poor prognosis and metastatic burden, indicating that YAP1 and SRC may provide valuable therapeutic targets and warrant further investigation." (PMID 36671452, 2022). "Besides, SRC mediates metastasis of prostate cancer cells in hypoxic condition." (PMID 35317831, 2022). "In addition, the high activation of SRC is also present in prostate cancer tissues." (PMID 32066485, 2020). "A study on prostate cancer bone metastasis identified FN1 as a key player in macrophage-induced anti-androgen resistance, proposing the FN1-integrin-SRC signaling axis as a potential therapeutic target for metastatic castration-resistant prostate cancer." (PMID 40380260, 2025). "Analysis indicated that the 9 hub genes (AKT1, HSP90AA1, SRC, GSK3β, VEGFR2, RHOA, ENO1, PKM, and IL-2) play roles in MF treatment by participating in signaling pathways related to prostate cancer, lipid and atherosclerosis, and insulin resistance." (PMID 40051434, 2025). "To explore PTK6-SRC crosstalk in prostate cancer, we examined colocalization of active PTK6 with active SRC in samples of transurethral resection of the prostate from patients who were diagnosed with CRPC." (PMID 36228719, 2022).
prostate carcinoma (continued). "In the cytoplasm, ligand‐bound AR interacts with protein kinases such as SRC and PI3K via its N terminus to initiate signal transduction pathways that modulate cellular proliferation and migration in prostate cancer cell lines." (PMID 33797847, 2021). "Of the individual proteins affected by lipidation, it was shown that alteration of palmitoylation and myristoylation sites change oncogenic potential of constitutively active SRC and FYN kinases in prostate cancer." (PMID 33572160, 2021). "In prohibition experiments with siRNAs of SRC and EPHB2, the cell motility and invasive capabilities of metastatic prostate cancer cells were attenuated (−15% in cell motility with siEPHB2 treatment, −49% in cell invasion with siSRC treatment)." (PMID 31805710, 2019). "In summary, this study identifies SEMA3C as a key secreted, autocrine growth factor that drives PCa growth and castration‐ and treatment‐resistant prostate cancer progression through activation of EGFR, HER2/ErbB2, MET, and c‐SRC tyrosine kinase pathways." (PMID 29348142, 2018). "Another SRC inhibitor, KX2-391, has been tested in phase II clinical trials for prostate cancer treatment, where it showed a relatively modest effect." (PMID 27418135, 2016). "In tumors, SRC activity is often increased and it correlates with SAM68 phosphorylation in different cancer types, including prostate cancer." (PMID 26273626, 2015). "Our study may also prompt investigators to look deeper into select kinases that phosphorylate AR, such as CDK1/5/9, ACK1, SRC, MAPK, as inhibition of these kinases in AR+ prostate cancers may provide patient benefit in combination with AR-targeted agents." (PMID 37456235, 2023). "In prostate cancer, active PTK6 and active SRC colocalize within the same cells." (PMID 36228719, 2022). "SRC is a large family of nonreceptor tyrosine kinases, and its overexpression occurs in various cancers, particularly prostate cancer." (PMID 35317831, 2022). "Therefore, this study aimed to examine the role of estrogen receptor in the activation of SRC, and the involvement of SRC and PI3K/AKT on invasion and colony formation of the androgen-independent prostate cancer cells PC-3." (PMID 33503805, 2021). "In addition, we have also checked the available human prostate cancer patient dataset for EPHB4 correlation with SRC and found that EPHB4 was positively correlated with SRC kinase in prostate cancer patients." (PMID 31641103, 2019). "Additionally, foreign studies have indicated that ER, located outside the nucleus, activates rapid‐response molecules like SRC and PI3K/AKT, thereby enhancing the tumorigenic potential of prostate cancer cells and increasing cell proliferation, migration, invasion, and tumor formation." (PMID 39349354, 2024). "In the current study, we characterized the regulation of β-tubulin isoform TUBB3 by SRC-mediated tyrosine phosphorylation and its role in the regulation of subcellular localization and protein stability of TUBB3 and mitotic spindle stability in prostate cancer cells." (PMID 35631517, 2022). "Activation of SRC, one of the non-receptor tyrosine kinase protein family, promotes cell survival, proliferation, and invasion in various human malignancies including lung, colon, and prostate cancer." (PMID 35873484, 2022). "Similarly, signaling of the nonreceptor tyrosine kinase SRC is involved in tumor metastasis and invasion of for example bone metastasis derived from breast and prostate cancer." (PMID 32082487, 2020). "The three major non-receptor tyrosine kinases, FAK, SRC and ETK, form the SRC tyrosine kinase complex, which in prostate cancer is suggested to play an important role in the aberrant activation of the androgen receptor (AR) by phosphorylation." (PMID 36673031, 2023).
melanoma (73 papers, 2010 to 2025). A malignant, usually aggressive tumor composed of atypical, neoplastic melanocytes. "The two ATP‐competitive protein tyrosine kinase inhibitors of SRC (bosutinib (Bos), dasatinib (Das)) were very effective resulting in the complete loss of the phospho‐activated SRC form (P‐Y416) in SK28R melanoma cells (WT, KO‐AhR, CA‐AhR; Fig EV3A)." (PMID 36305167, 2022). "Cell migration and invasion through FAK and SRC signaling pathway is implicated in focal adhesion turn-over in melanoma." (PMID 27472394, 2016). "As well as cell autonomous effects, drug-induced stimulation of melanoma-associated fibroblasts stimulates matrix remodelling and, in this case, signals via integrins to increase SRC and FAK activity." (PMID 27835901, 2016). "Previous studies have linked SRC inhibition with the control of proliferation in melanoma cells and SRC inhibition induces apoptosis in melanoma cells." (PMID 25594008, 2014). "Interestingly SRC has been implicated in BRAF inhibitor resistance in BRAF‐mutant melanoma cells and patient‐derived tissues." (PMID 30979792, 2019). "Additionally, SRC activation was implicated with primary resistance to PLX4032 in patient-derived melanoma cells." (PMID 22984562, 2012). "Overall, phase I/II trials in advanced melanoma have also observed partial and minor responses to SRC inhibitors." (PMID 40399946, 2025). "The interaction of CD318 with SRC has been well studied, and has shown that the CD318/SRC axis contributes to the development of multiple cancers, including breast, melanoma, and lung." (PMID 40725832, 2025). "Blocking STAT3 or SRC signaling decreases key cell survival proteins, including Bcl-xL and Mcl-1 (Myeloid cell leukemia-1), precipitating apoptosis in melanoma cells." (PMID 40399946, 2025). "Among them, SRC activation has been implicated in resistance to drugs targeting the MAPK pathway, including EGFRi in KRAS-mutated CRC or BRAFi in BRAF-mutated melanoma." (PMID 40481178, 2025). "Inhibition of the FAK/SRC pathway with SRC inhibitors preserves membranous E-cadherin localization and effectively reduces melanoma cell migration." (PMID 40399946, 2025). "The efficacy of SRC inhibitors, such as dasatinib, nilotinib, and saracatinib, has been evaluated in clinical trials for melanoma." (PMID 40399946, 2025). "Our evaluation of different BRAFi-based drug combinations suggests that inhibiting SRC kinases with saracatinib can sensitize, de-differentiated melanomas to BRAFi." (PMID 36271142, 2022). "This study reports that the AhR/SRC axis constitutes a therapeutic vulnerability in BRAFi‐resistant melanoma." (PMID 36305167, 2022). "Treatment of SK28R melanoma cells with increasing doses of SRC inhibitors (Bos or Das) at different doses (10–500 nM) in combination with increasing doses of Vem significantly increased BRAFi sensitivity." (PMID 36305167, 2022). "It warrants future clinical studies targeting the AhR‐dependent SRC/FAK/EGFR axis in combination with BRAFi/MEKi double blockade to re‐sensitize melanoma to standard melanoma treatment and counteract resistance." (PMID 36305167, 2022). "Using pharmacological inhibition of integrins αvβ3 and αvβ5, FAK and SRC, we also confirmed the sequential activation of the three members of the pathway in A375 human melanoma cells." (PMID 36229674, 2022). "We shed light on this connection by showing that RAC1 and SRC critically maintain melanoma de-differentiation." (PMID 36271142, 2022). "We found that only de-differentiated cell lines were sensitized to BRAFi by SRC inhibition (SRCi), while the differentiated melanomas only showed a modest decrease in the AUC compared to that of VEM alone." (PMID 36271142, 2022). "In particular, we pinpoint the crosstalk between AhR and SRC in reshaping cell fate and identify the AhR/SRC axis as a new therapeutic vulnerability for the treatment of BRAFi‐resistant melanoma." (PMID 36305167, 2022).
melanoma (continued). "Together, AhR‐dependent transcriptional reprogramming and SRC activation triggers the cell plasticity of BRAFi‐resistant melanoma." (PMID 36305167, 2022). "Using a preclinical BRAFi‐resistant PDX melanoma model, we demonstrate that SRC inhibition with dasatinib significantly re‐sensitizes melanoma cells to BRAFi." (PMID 36305167, 2022). "Among the reported mechanisms involved, are increased HGF release by host fibroblasts and the promotion of matrix production and remodeling leading to elevated integrin β1/FAK/SRC signaling in melanoma cells." (PMID 35440004, 2022). "The identification herein of the AhR/SRC activation loop in BRAFi‐resistant melanoma gives rationale to these studies filling an important gap to understand cell plasticity and propose innovative therapeutic regimens." (PMID 36305167, 2022). "Partial SRC knockdown in metastatic human melanoma cells (MA2) significantly inhibited YAP/TAZ transcriptional activity and reduced the number of metastases that formed." (PMID 30559289, 2019). "We examined if the “paradoxical” activation of the MAPK pathway is a common response to SRC inhibition in these melanoma cells." (PMID 31040916, 2019). "This did indicate that endogenous GH and the JAK2, STAT5, and SRC signaling pathways were critical for melanoma survival." (PMID 31547367, 2019). "Consistently, we found that melanoma cells attached and spreading on either fibronectin or collagen had significantly higher levels of activated SRC than cells adhering in an integrin-independent manner to poly-l-lysine." (PMID 30559289, 2019). "Stable expression of the LATS-insensitive YAP2SA in the metastatic melanoma cells with SRC knockdown was unable to rescue metastasis, despite significantly enhancing YAP/TAZ activity." (PMID 30559289, 2019). "Additional studies showed that SRC-I1 (SRC inhibitor-1) was inactive on patient-derived BRAFV600E mutant melanoma cells resistant to vemurafenib, but enhanced the activity of the pan-RAF inhibitor TAK632 against these cells." (PMID 31040916, 2019). "Consistent with the enrichment result of tyrosine sites, kinome scale siRNA screening indicated that SRC\MEK5 cascade promotes the phosphorylation of BMK1 in response to CIBM in melanoma." (PMID 28387310, 2017). "Intriguingly, a SRC mutation (99% frequency, probably copy-neutral LOH), which is a very infrequent mutation in melanoma, was detected in Tumor #3, which was a rare acral CBNs with a cystic degeneration in the central part of the tumor." (PMID 27057633, 2016). "The list comprises of several well-known melanoma-associated-oncogenes including RAF1, AURKA and SRC along with putative novel oncogenes." (PMID 26558755, 2015). "Seventeen percent (19/112) of melanoma samples were positive for SRC kinase expression, combined with high expression of ANXA1, CAV-1 and EphA2." (PMID 25594008, 2014). "All these networks were associated to intracellular signaling pathways known to be active in MDSCs (SRC, Grb2, Ras, Stat3, NF-κB and MAPKs), some of them melanoma MDSC-specific targets such as STAT3." (PMID 25151659, 2014). "In a study of 35 melanomas, phospho-SRC (p-SRC) was detected in approximately 50 % (17/35) by immunohistochemical analysis." (PMID 25594008, 2014). "The activation of MET and SRC signaling was detected in two patient-derived melanoma cell lines with BRAFV600E that were resistant to BRAF inhibitor PLX4032." (PMID 24743024, 2014). "Transient overexpression of miR-31 in various melanoma cell lines inhibited cell migration and invasion, supporting a role for miR-31 as a tumor-suppressive miR that targets multiple oncogenes such as SRC, MET, NIK and RAB27a." (PMID 22948084, 2012). "Activated SRC was also detected in cutaneous, mucosal and metastatic melanoma, and its inhibition by dasatinib or bosutinib blocked the growth of several melanoma cell lines." (PMID 20663135, 2010).